LANCL1 (LanC like glutathione S-transferase 1)
Description:
Functions as a glutathione transferase. Catalyzes conjugation of the glutathione (GSH) to artificial substrates 1-chloro-2,4-dinitrobenzene (CDNB) and p-nitrophenyl acetate. Mitigates neuronal oxidative stress during normal postnatal development and in response to oxidative stresses probably through GSH antioxidant defense mechanism (By similarity). May play a role in EPS8 signaling. Binds glutathione.
Synonyms: p40; GPR69A
Tractability: Small molecule: a structure with a bound ligand is known; it has a binding pocket of medium quality. Antibody: UniProt places it where antibodies can reach, with high confidence; its Gene Ontology location is reachable by antibodies, with high confidence. PROTAC: ubiquitination databases record sites on it; its protein half-life has been measured.
Target class: Enzyme; Transferase
Gene: Protein-coding gene on chromosome 2 (210,427,131 to 210,477,652, reverse strand). Ensembl gene ENSG00000115365.
Subcellular location: Cytoplasm; Cell membrane
Subcellular location (Human Protein Atlas): Basal body; End piece; Microtubules; Primary cilium; Flagellar centriole
Gene Ontology:
Molecular function: glutathione binding; low-density lipoprotein particle receptor binding; protein binding; SH3 domain binding; zinc ion binding; G protein-coupled receptor activity; glutathione transferase activity
Biological process: G protein-coupled receptor signaling pathway; cellular detoxification; carbohydrate metabolic process; peptide modification
Cellular component: cytoplasm; plasma membrane
Genetic constraint (gnomAD): Loss-of-function variants: 43 observed, 42.51 expected, observed/expected ratio (o/e) 1.01, 90% interval 0.79 to 1.3. The upper end of that interval is the gene's LOEUF score, 1.3, which puts it in group 5 of 6, group 1 being the genes least tolerant of losing a copy. Missense variants: 489 observed, 460.29 expected, observed/expected ratio (o/e) 1.06, 90% interval 0.99 to 1.14. Synonymous variants: 178 observed, 175.06 expected, observed/expected ratio (o/e) 1.02, 90% interval 0.9 to 1.15.
Homologues: Orthologues: macaque LANCL1 (99% identical), chimpanzee LANCL1 (99% identical), rabbit LANCL1 (95% identical), pig LANCL1 (93% identical), guinea pig LANCL1 (92% identical), mouse Lancl1 (91% identical), rat Lancl1 (91% identical), dog LANCL1 (91% identical), tropical clawed frog lancl1 (67% identical), zebrafish lancl1 (65% identical), Drosophila melanogaster CG2061 (34% identical). Paralogues in human: LANCL2 (57% identical), LANCL3 (36% identical).